ITGB2 (integrin subunit beta 2)
Description:
Integrin ITGAL:ITGB2 is a receptor for ICAM1, ICAM2 and ICAM3. Integrin ITGAL:ITGB2 is also a receptor for the secreted form of ubiquitin-like protein ISG15; the interaction is mediated by ITGAL. Integrins ITGAM:ITGB2 and ITGAX:ITGB2 are receptors for the iC3b fragment of the third complement component and for fibrinogen. Integrin ITGAX:ITGB2 recognizes the sequence G-P-R in fibrinogen alpha-chain. Integrin ITGAM:ITGB2 recognizes P1 and P2 peptides of fibrinogen gamma chain. Integrin ITGAM:ITGB2 is also a receptor for factor X. Integrin ITGAD:ITGB2 is a receptor for ICAM3 and VCAM1. Contributes to natural killer cell cytotoxicity. Involved in leukocyte adhesion and transmigration of leukocytes including T-cells and neutrophils. Triggers neutrophil transmigration during lung injury through PTK2B/PYK2-mediated activation. Integrin ITGAL:ITGB2 in association with ICAM3, contributes to apoptotic neutrophil phagocytosis by macrophages. In association with alpha subunit ITGAM/CD11b, required for CD177-PRTN3-mediated activation of TNF primed neutrophils. Integrins ITGAX:ITGB2 functions as a receptor of the erythrocyte-specific adhesion molecule ICAM4 and mediates erythrophagocytosis. Integrins ITGAX:ITGB2 functions as a receptor of the neuron-specific adhesion molecule ICAM5 ensuring neuron cell-leukocyte adhesion. Integrin ITGAL:ITGB2 functions as a receptor of ICAM1 by acting as a platform at the immunological synapse to translate TCR engagement and density of the ITGAL ligand ICAM1 into graded adhesion. Integrin ITGAM:ITGB2/MAC-1 complex functions as a signaling receptor for the ligand receptor ICAM1, ensuring adhesion between stimulated neutrophils and stimulated endothelial cells. Integrin ITGAL/ITGB2 that functions as a signaling receptor of ICAM2, ensuring leukocyte cell-cell adhesion on resting cells.
Synonyms: CD18; MFI7; LFA-1; MAC-1; LAD; LCAMB; MF17
Tractability: Small molecule: an approved drug acts on it; a structure with a bound ligand is known; a high-quality ligand is known; it has a binding pocket of medium quality; it belongs to a druggable protein family. Antibody: a drug acting on it is in phase 2 or 3 trials; UniProt places it where antibodies can reach, with high confidence; its Gene Ontology location is reachable by antibodies, with high confidence; UniProt predicts a signal peptide or a membrane-spanning region; the Human Protein Atlas places it where antibodies can reach. PROTAC: ubiquitination databases record sites on it; its protein half-life has been measured; a small molecule that binds it is known.
Target class: Membrane receptor
Gene: Protein-coding gene on chromosome 21 (44,885,948 to 44,932,079, reverse strand). Ensembl gene ENSG00000160255.
Subcellular location: Cell membrane; Membrane raft
Subcellular location (Human Protein Atlas): Plasma membrane; Rods & Rings
Pathways (Reactome):
Immune System: Immunoregulatory interactions between a Lymphoid and a non-Lymphoid cell; Interleukin-4 and Interleukin-13 signaling; Neutrophil degranulation; Toll Like Receptor 4 (TLR4) Cascade
Extracellular matrix organization: Integrin cell surface interactions
Hemostasis: Cell surface interactions at the vascular wall
Gene Ontology:
Molecular function: cell adhesion molecule binding; cell adhesion receptor activity; heat shock protein binding; ICAM-3 receptor activity; protein binding; protein kinase binding; amyloid-beta binding; cargo receptor activity; complement component C3b binding; integrin binding; protein-containing complex binding
Biological process: cell adhesion; cell adhesion mediated by integrin; cell-cell adhesion mediated by integrin; cell-matrix adhesion; endodermal cell differentiation; heterotypic cell-cell adhesion; integrin-mediated signaling pathway; leukocyte adhesion to vascular endothelial cell; leukocyte cell-cell adhesion; neuron cell-cell adhesion; neutrophil chemotaxis; neutrophil migration; phagocytosis; positive regulation of neutrophil degranulation; positive regulation of superoxide anion generation; receptor clustering; regulation of peptidyl-tyrosine phosphorylation; amyloid-beta clearance; apoptotic process; cell-cell adhesion; cell-cell signaling; cellular response to low-density lipoprotein particle stimulus; inflammatory response; microglial cell activation; negative regulation of dopamine metabolic process; and 13 more
Cellular component: cell surface; extracellular exosome; extracellular vesicle; integrin alphaD-beta2 complex; integrin alphaL-beta2 complex; integrin alphaM-beta2 complex; integrin alphaX-beta2 complex; membrane; membrane raft; plasma membrane; plasma membrane raft; receptor complex; external side of plasma membrane; ficolin-1-rich granule membrane; focal adhesion; integrin complex; specific granule membrane; tertiary granule membrane
Genetic constraint (gnomAD): Loss-of-function variants: 54 observed, 83.59 expected, observed/expected ratio (o/e) 0.65, 90% interval 0.52 to 0.81. The upper end of that interval is the gene's LOEUF score, 0.81, which puts it in group 3 of 6, group 1 being the genes least tolerant of losing a copy. Missense variants: 939 observed, 1,083 expected, observed/expected ratio (o/e) 0.87, 90% interval 0.82 to 0.92. Synonymous variants: 452 observed, 459 expected, observed/expected ratio (o/e) 0.98, 90% interval 0.91 to 1.06.
Homologues: Orthologues: chimpanzee ITGB2 (98% identical), macaque ITGB2 (86% identical), pig ITGB2 (82% identical), mouse Itgb2 (81% identical), dog ITGB2 (80% identical), rat Itgb2 (80% identical), guinea pig ITGB2 (79% identical), rabbit ITGB2 (75% identical), tropical clawed frog itgb2 (57% identical), zebrafish itgb2 (49% identical), Drosophila melanogaster mys (37% identical), Caenorhabditis elegans pat-3 (36% identical). Paralogues in human: ITGB7 (47% identical), ITGB1 (45% identical), ITGB3 (39% identical), ITGB6 (38% identical), ITGB5 (37% identical), ITGB4 (34% identical), ITGB8 (30% identical), ITGBL1 (16% identical).
Diseases named in the same sentence as ITGB2 in open-access papers:
ITGB2 is named in the same sentence as 280 diseases in open-access papers, as found by Europe PMC text mining. Sharing a sentence is not in itself a finding about the gene and the disease. The quoted sentences say what the papers report.
leukocyte adhesion deficiency (28 papers, 2004 to 2025). Leukocyte adhesion deficiency (LAD) is a primary immunodeficiency characterized by defects in the leukocyte adhesion process, marked leukocytosis and recurrent infections. "Mutations in the human ITGB2 gene encoding the cell surface molecule CD18 have been associated with human leukocyte adhesion deficiency (LAD), a disorder characterized by recurrent infections and reduced neutrophil motility." (PMID 37047441, 2023). "Genetic deletion of this gene was reported to reduce aortic lesion size in mice, while mutations in ITGB2 cause leukocyte adhesion deficiency." (PMID 35694160, 2022). "ITGB2 plays a vital role in immune response, silencing ITGB2 leads to leukocyte adhesion deficiency and IRF7 is associated with immunodeficiency, enhanced expression of ACSS3 will help the migrated cells to evade from the immune elimination." (PMID 35685372, 2022). "Accordingly, CD18 knock-out (KO) zebrafish larvae displayed the key symptoms of patients suffering from leukocyte adhesion deficiency (LAD) type I due to defects in ITGB2, the gene for CD18." (PMID 34557186, 2021). "It plays an important role in the immune response, and defects in ITGB2 cause leukocyte adhesion deficiency." (PMID 34093637, 2021). "ITGB2 is the only gene which is directly related to the disease known as leukocyte adhesion deficiency (LAD), an immunodeficiency which is characterized mainly by the nonmobilization or migration of leukocytes, specifically neutrophils, to lesion sites." (PMID 31772502, 2019). "Only ITGB2 gave a positive result with the clinical features of leukocyte adhesion deficiency, related to the route of transendothelial migration of leukocytes (hsa04670 from KEGG)." (PMID 31772502, 2019). "A mutation in the human CD18 gene (ITGB2) leads to a condition called leukocyte adhesion deficiency, which is characterized by neutrophilia and impaired neutrophil recruitment to sites of infection." (PMID 28873429, 2017). "The ITGB2 gene encodes integrin subunit beta 2 (also known as archetypal innate immune receptor CD11b/CD18), which plays an important role in immune response, and defects in this gene may cause leukocyte adhesion deficiency." (PMID 37188670, 2023). "ITGB2 protein genetic defects in ITGB2 are associated with leukocyte adhesion deficiency." (PMID 35401223, 2022). "Genetic defects in the ITGB2 gene, coding for CD18, results in a disorder marked by recurrent bacterial infections known as leukocyte adhesion deficiency (LAD) type I." (PMID 40001541, 2025). "In humans, mutations in ITGB2, the gene for CD18, result in leukocyte adhesion deficiency (LAD) type I which is characterized by neutrophilia, impaired wound healing, and recurrent infections caused by compromised neutrophil recruitment to sites of infection." (PMID 34557186, 2021).
breast carcinoma (26 papers, 2006 to 2025). "Previous studies have shown that ITGB2 is involved in the occurrence, invasion and metastasis of various cancer types (such as liver, colon, breast cancer and leukemia)." (PMID 38345576, 2024). "Research has shown that ITGB2 is highly expressed in a number of cancers, such as colorectal cancer, renal clear-cell carcinoma, papillary thyroid cancer, and breast cancer." (PMID 38534733, 2024). "Another study found that YAP promoted breast cancer metastasis through the induction of the ITGB2 gene." (PMID 38473214, 2024). "In general, ITGB2 is involved in the development, metastasis, and invasion of a wide range of tumor types, including liver cancer, colon cancer, breast cancer, and leukemia." (PMID 38385005, 2024). "It has been reported that the lack of ITGB2 plays a positive role in preventing autoimmune diabetes, and the high expression of ITGB2 promotes the migration and invasion of breast cancer." (PMID 36714574, 2022). "Overall, these results suggest that the SMAD3-dependent gene signature is present in hypoxic tumors and that VIM and ITGB2 are better predictors of metastasis or cancer recurrence in lung carcinoma and breast cancer than RHOB." (PMID 35681731, 2022). "It was also observed that ITGB2 indirectly promotes the proliferation of oral squamous cell carcinoma by regulating cancer-associated fibroblasts and mediates YAP-induced breast cancer cell transendothelial invasion." (PMID 36362654, 2022). "For example, in the case of ITGB2, IHC indicates that ITGB2 is only overexpressed in gliomas and prostate cancers whereas RNA-seq identifies ITGB2 elevation in breast cancer, glioma, head and neck cancer, renal cancer and stomach cancer." (PMID 30046394, 2018). "This overexpression is strongly correlated with poorer overall survival in TNBC patients, suggesting that ITGB2 could serve as a prognostic biomarker for this aggressive breast cancer subtype." (PMID 40071217, 2025). "Moreover, Park & al. demonstrated in MCF10 breast cancer cells overexpressing SRSF6 that ITGA5, ITGB2 and ITGB6 were overexpressed and alternative splicing variants of ITGB2, ITGB4, SRSF6 and ATXN2 were detected." (PMID 37904233, 2023). "In addition, ITGB2 was proved to promote the effects of the migration capability and invasion capability of breast cancer via biological function experiments." (PMID 36362654, 2022). "Using the SurvExpress web tool, we found that RHOB expression had conflicted predictive value for cancer progression, whereas high VIM and ITGB2 expression were positively correlated with low metastasis-free/recurrence-free survival in lung adenocarcinoma and breast cancer cohorts." (PMID 35681731, 2022). "Upregulation of ITGB2 promotes the migration and invasion in breast cancer." (PMID 32787954, 2020). "Through the acquisition of adhesion ability, the integrins ITGB2, ITGB4, and ITGA10 may promote the attachment of breast cancer cells to the extracellular matrix and thereby enhance metastasis." (PMID 36910659, 2023). "The genes belonged to a variety of biological functions such as cell motility and invasion (Cdc42, ITGB2), cell cycle (EGR1, RRM2) or signal transduction (VEGFC), indicating that expression of E-cadh and P-cadh in breast cancer cells have a significant impact on their overall genetic program." (PMID 19257890, 2009). "In addition, GEO analysis showed that ITGB2 was also overexpressed in prostate cancer, breast cancer and ovarian cancer, indicating it is not an exclusive phenomenon in OSCC." (PMID 33204328, 2020). "ITGB2 plays a vital role in in various disorders covering nasopharyngeal carcinoma, NSCLC (non-small cell lung cancer), glioma, breast cancer, and osteosarcoma, and non-tumor diseases, including the SSc (systemic sclerosis) and NEC (necrotizing enterocolitis) of infants." (PMID 36980477, 2023).
atherosclerosis (25 papers, 2012 to 2025). A disease characterized by the build-up of fatty material and calcium deposition in the arterial wall resulting in partial or complete occlusion of the arterial lumen. "The lncRNA AC078850.1 mediates cellular pyroptosis in atherosclerosis by increasing HIF‐1α‐mediated transcription of the ITGB2 gene." (PMID 40032652, 2025). "Taken together, the data in this study unveiled that lncRNA AC078850.1 mediated pyroptosis in atherosclerosis via increasing HIF-1α-mediated ITGB2 gene transcription." (PMID 37371830, 2023). "From the vast array of genes that are associated with this condition, AGT, LPL, ITGB2, IRS were identified to play vital role in the pathogenesis of atherosclerosis." (PMID 35241081, 2022). "A total of 6 intersecting drugs targeting 3 genes, CSF1R, CTSS, and ITGB2, were selected as candidate druggable molecular targets for atherosclerosis." (PMID 35811739, 2022). "Previous research has illustrated that ITGB2 enhances the cross-cell migration of white blood cells in both animal and cell culture experiments, impairing endothelial barrier integrity and participating in atherosclerosis development." (PMID 39055656, 2024). "Firstly, the Lasso Cox regression model for the cluster DEGs of atherosclerotic samples from GSE28829 was conducted to investigate an optimum linear combination in predicting advanced atherosclerosis, with coefficients 0.6626 and 0.0228 for ITGB2 and C1QA, respectively." (PMID 35811739, 2022). "ITGB2 has roles in autoimmunity, diabetes, and atherosclerosis." (PMID 33946285, 2021). "ITGB2 (CD18), an adhesion molecule of the integrin family and a key marker of NK cells maturation, plays a crucial role in mediating adhesion between inflammatory cells and endothelial cells, inflammatory cell chemotaxis, and other processes involved in the early stages of atherosclerosis." (PMID 40276515, 2025). "Additionally, C1QA and ITGB2 could not only differentiate early and advanced atherosclerosis but also highly specific and sensitive DEGs for predicting plaque rupture." (PMID 35811739, 2022). "Thus, exhibiting a direct relationship of ITGB2 with atherosclerosis." (PMID 35241081, 2022). "Therefore, ITGB2 may serve as a common target for gout with atherosclerosis." (PMID 38368442, 2024). "Analysis of tissue expression data on porcine atherosclerosis induced by high lipid factors indicates that TYROBP, ITGB2, and ITGAM are key genes influencing the progression of ankylosing spondylitis." (PMID 38382092, 2024). "Of these, after gene expression verification, only ITGB2, CTSS, LY86, and ITGAX were found to be highly expressed in both atherosclerosis and AAA." (PMID 39560590, 2024). "These six hub genes, TYROBP, ITGAM, ITGB2, CD86, PLEK, LCP2 may be important biomarkers for the progression of atherosclerosis and potential treatment targets." (PMID 38382092, 2024). "Studies in animal models and humans have demonstrated that CTSS, ITGB2, and TYROBP are markers for obesity and represent possible molecular links between obesity and obesity comorbidities, such as cardiovascular diseases and atherosclerosis." (PMID 37458462, 2023). "In addition, ITGB2 and TYROBP genes’ expression levels correlate with blood levels of low-density lipoprotein cholesterol (LDL-C) in the mini-pig atherosclerosis model." (PMID 37458462, 2023). "RUNX1, which may function as an important TF in the pathogenesis of patients with RA complicated with atherosclerosis, was predicted to participate in the regulation of the two hub genes CSF1R and ITGB2." (PMID 35304503, 2022). "In addition, we revealed for the first time the correlations between ITGB2/ITGAM and various types of immune cells in atherosclerosis plaques by immune cell infiltration analysis." (PMID 35656397, 2022). "This suggests that ITGAM and ITGB2 may play an important role in the occurrence of IPH, immune cell infiltration, and the progression of atherosclerosis." (PMID 35656397, 2022).
atherosclerosis (continued). "Moreover, as a ROS-related protein, ITGB2 could interact with multiple genes (e.g., HIF-1α) to promote ROS production, NLRP3 inflammasome activation, pyroptosis, and foam cell formation in macrophages, suggesting its potential role in the progression of atherosclerosis." (PMID 41348730, 2025).
Sepsis (18 papers, 2011 to 2025). Sepsis is defined as life-threatening organ dysfunction caused by a dysregulated host response to infection. "Collectively, these findings indicate that dysregulation of the GM may facilitate the activation of NETs, while the expression of integrins ITGAM and ITGB2 is closely linked to the progression of sepsis-induced ALI." (PMID 41586375, 2025). "ITGB2 has been identified as an important factor in the inflammatory response to sepsis." (PMID 32174955, 2020). "Importantly, ITGAM and ITGB2 may emerge as promising therapeutic targets for mitigating sepsis-induced ALI, while microbiota-based interventions such as FMT offer translational potential as adjunctive therapeutic strategies." (PMID 41586375, 2025). "Collectively, these findings indicate that sepsis induces robust NET formation, while the GM modulates the expression of ITGAM and ITGB2, thereby preserving endothelial structure and barrier integrity in the presence of NETs." (PMID 41586375, 2025). "We unveil a novel gut microbiota-NET-integrin axis in sepsis-induced ALI, where microbial dysbiosis promotes NET-mediated suppression of ITGAM/ITGB2, leading to endothelial barrier failure." (PMID 41586375, 2025). "CLP-induced sepsis triggered severe pulmonary edema, neutrophil infiltration, and NET accumulation, alongside downregulation of ITGAM/ITGB2 and tight junction proteins (β-catenin/ZO-1/VE-cadherin)." (PMID 41586375, 2025). "In conclusion, our study reveals a novel mechanism whereby gut dysbiosis exacerbates sepsis-induced ALI by promoting NET formation and downregulating ITGAM and ITGB2, leading to compromised pulmonary endothelial barrier function." (PMID 41586375, 2025). "Against this backdrop, the present study investigates whether GM dysbiosis exacerbates sepsis-induced ALI by promoting NET formation and suppressing the expression of the integrins ITGAM and ITGB2, thereby disrupting pulmonary endothelial barrier integrity." (PMID 41586375, 2025).